CDX2 (caudal type homeobox 2)
Diseases named in the same sentence as CDX2 in open-access papers (continued):
Sharing a sentence is not in itself a finding about the gene and the disease.
signet ring cell adenocarcinoma (7 papers, 2012 to 2025). "Villin, CDX2, COX2, and SATB2 are specific markers derived from gastrointestinal adenocarcinoma, including signet ring cell carcinoma, and are often used to identify tumors from other systems, including the breast, lung, and the female reproductive system." (PMID 37337182, 2023). "Because in intestinal metaplasia of the stomach, CDX2 and Reg IV expression are well correlated, GC cell lines established from diffuse type GC or signet ring cell carcinoma may not be suitable for the analysis of Reg IV induction by CDX2." (PMID 23133598, 2012). "The absence of CDX-2 (-), CK20 (-), CK7 (-), SATB2 (-), and PAS (-) rules out metastasis from signet ring cell carcinoma of the digestive system." (PMID 39723371, 2024). "Most of these cervical intestinal and signet ring cell adenocarcinoma have been studied with immunohistochemistry and shown to be diffusely positive with CK7 and focally or diffusely positive with CK20 and CDX2 while being negative for p16 antigens." (PMID 28826403, 2017).
carcinoids (6 papers, 2009 to 2025). "Moreover, CDX2, which is expressed in the nuclei of intestinal epithelial cells, was detected in three out of five strumal carcinoids in which it was assessed (60%)." (PMID 35528006, 2022). "In our case, the exceptionally rare Cdx-2 stain positivity was found as well, albeit no GI origin of carcinoid tumor cells was detected." (PMID 33317491, 2020). "While TTF1 and caudal type homeobox 2 (CDX2) can assist in distinguishing between primary and metastatic carcinoid tumors, the distinction is not always marked." (PMID 40069785, 2025). "The carcinoid tumor component was strongly positive for CD56, chromogranin and synaptophysin, weakly positive for pancytokeratin, and negative for carbonic anhydrase IX, CD99, CDX2, cytokeratin 7, cytokeratin 20 and smooth muscle actin." (PMID 19523243, 2009). "The carcinoid tumor component was strongly and diffusely immunoreactive (3+, cytoplasmic staining) for CD56, chromogranin and synaptophysin; weakly and focally immunoreactive (1+, cytoplasmic staining) for pancytokeratin; and negative for CA-IX, CD99, CDX2, CK7, CK20 and SMA." (PMID 19523243, 2009).
ovarian mucinous tumors (6 papers, 2013 to 2025). "In Lee’s opinion, the coordinated expression of CK7, CK20, and CDX2 might be helpful in differentiating metastatic urachal carcinoma from primary ovarian mucinous tumor." (PMID 23914849, 2013). "Although 30% of mucinous ovarian tumors (n = 104) had IHC performed for CK7, CK20, CDX2, SATB2, and PAX8 in a prior study, we were unable to perform this diagnostic panel on all cases and could not confirm whether they were done as part of routine pathologic assessment." (PMID 36222710, 2022).
ovarian tumor (6 papers, 2013 to 2025). "A repeat cell block examination of the ascites taken during the operation showed positivity of CK7, ER, and PAX8 and negativity of CK20 and CDX-2, leading to the diagnosis of a possible uterine or ovarian tumor." (PMID 41018407, 2025). "A cell block analysis of the ascites taken during the operation showed positivity of CK7, ER, and PAX8 and negativity of CK20 and CDX-2, leading to the diagnosis of a possible uterine or ovarian tumor." (PMID 41018407, 2025). "Thus, a finding of diffusely and strongly positive CDX2 plays a key role in excluding the primary ovarian tumor." (PMID 23914849, 2013). "Immunohistochemistry staining showed that ovarian tumor was CK7-negative, CK20-positive, and CDX2-positive, suggesting metastasis of cecal cancer." (PMID 35321695, 2022). "Immunohistochemistry staining showed that the ovarian tumor was CK7-negative, CK20-positive, and CDX2-positive." (PMID 35321695, 2022). "Staining for SATB2 is useful in ovarian tumors with morphologic evidence of intestinal differentiation, or with expression of CDX2 or CK20, as most cases (98%) are typically negative." (PMID 31771640, 2019). "Immunohistochemistry staining showed that the ovarian tumor was CK7-positive, CK20-negative and CDX2-negative." (PMID 35321695, 2022).
pancreatic ductal adenocarcinoma (6 papers, 2012 to 2025). An infiltrating adenocarcinoma that arises from the epithelial cells of the pancreas. "Among the pancreatic ductal adenocarcinoma cases, 71.42% demonstrated weak CDX2 positivity (80%) or moderate CDX2 positivity (20%)." (PMID 37174934, 2023). "With regard to CDX2 expression in normal pancreas and pancreatic ductal adenocarcinoma (PDAC), data extracted from several previous studies are very inconsistent." (PMID 24489794, 2014). "As for CDX2 expression in pancreatic ductal adenocarcinomas, there appears to be somewhat less agreement in the literature." (PMID 22268990, 2012). "Pancreatic ductal adenocarcinoma (PDAC) is one of the most common causes for adenocarcinomas of unknown origin, but CDX2 expression in pancreatic disease remains unclear." (PMID 24489794, 2014). "Using NetRank, we identified seven genes (STAT3, FOS, JUN, SP1, CDX2, CEBPA, and BRCA1) as most relevant for predicting survival in patients with pancreatic ductal adenocarcinoma." (PMID 22615549, 2012).
atrophic gastritis (5 papers, 2016 to 2024). "In this study, we showed that HFD feeding induces Cdx2 and Muc2 expression associated with increased leptin levels, suggesting the possibility that leptin acts to suppress cellular protection against gastric mucosal malignancies in the early stage of atrophic gastritis." (PMID 26839577, 2016). "RT-qPCR found that compared with adjacent cancer tissues, CDX2 was highly expressed in GC tissues and atrophic gastritis gastric tissues (p < 0.05)." (PMID 33292210, 2020). "miR-365 was poorly expressed in GC and atrophic gastritis tissues and GC cell lines, while TLR4, CDX2 and IRF3 were overexpressed." (PMID 33292210, 2020). "miR-365, TLR4, CDX2 and IPF3 expression was determined in GC and atrophic gastritis tissues and cells." (PMID 33292210, 2020).
esophagitis (5 papers, 2008 to 2022). An acute or chronic inflammatory disease affecting the esophageal wall. "We also demonstrated that the BMP4/pSMAD pathway is upregulated in the surgical rat esophagitis-IM model 20–22 weeks post esophago-jejunostomy and that BMP4 overexpression together with CDX2 induces upregulation of intestinal type of genes in a surgical mouse esophagitis-IM model." (PMID 34718471, 2022). "CDX2 mRNA is also up regulated in inflamed squamous epithelium (esophagitis) preceding the development of BE suggesting that CDX2 may play an initiating role in the development of metaplasia." (PMID 25870690, 2014). "However, one previous study showed that a low level of Cdx2 mRNA was detected in biopsy samples of esophageal squamous epithelium in patients with esophagitis." (PMID 18190713, 2008). "Similar to human tissue, the rat esophageal tissues showed stepwise increases in the expression of KLF5, Cdx2, MUC2 and villin in the order of normal esophageal, esophagitis and BE squamous epithelium based on immunohistochemical analysis." (PMID 31632504, 2019). "Results of immunohistochemistry studies performed to analyze the expression of KLF5, Cdx2, MUC2 and villin in the rat models showed a marked increase in nuclear staining in BE mucosa compared to that in normal esophageal and esophagitis mucosa." (PMID 31632504, 2019). "In the assessment of cell lineage distribution, evaluation of the expression of the intestinal markers Cdx2, MUC2 and villin in human BE squamous epithelium revealed increasing expression of Cdx2, MUC2 and villin in the order of normal esophageal, esophagitis and BE tissues." (PMID 31632504, 2019).
gastroesophageal reflux (5 papers, 2009 to 2016). "In humans, Cdx2 is expressed in BE and can be detected very early in the disease process, in the setting of reflux esophagitis." (PMID 26460825, 2015). "Different studies, using animal models, have shown that CDX2 expression may be induced by bile acids, present in the gastroesophageal reflux, leading to differentiation reprogramming of squamous epithelium to a glandular intestinal one." (PMID 27766003, 2016). "In this experimental study, the expression of Cdx2 protein was tested over the whole spectrum of phenotypic lesions detected in a surgical murine model of esophago-gastroduodenal anastomosis (EGDA) resulting in longstanding esophageal reflux of gastro-duodenal contents." (PMID 19664209, 2009). "BE is associated with gastroesophageal reflux which might change the expression profile of key transcription factors involved in the establishment of tissue differentiation, namely, SOX2 (associated with esophageal and gastric differentiation) and CDX2 (associated with intestinal differentiation)." (PMID 27766003, 2016).
head and neck squamous cell carcinoma (5 papers, 2011 to 2023). A squamous cell carcinoma that arises from any of the following anatomic sites: lip and oral cavity, nasal cavity, paranasal sinuses, pharynx, larynx, and salivary glands. "In this study, we assessed associations between five polymorphisms (Cdx2, FokI, BsmI, ApaI, and TaqI) and progression-free survival in patients with head and neck squamous cell carcinoma (HNSCC)." (PMID 22242137, 2011). "Another study also confirms that CDX2/p300 enhances NK cell-mediated immunotherapy against head and neck squamous cell carcinoma in vitro; the findings indicate that CDX2 stimulated NK cell migration, cytotoxicity and infiltration by upregulating CXCL14 in HNSCC tissues." (PMID 36980527, 2023).
medullary carcinomas (5 papers, 2012 to 2025). "In the medullary carcinoma subgroup, a significant difference in CDX2 expression rates was observed between cut-offs." (PMID 35328309, 2022). "There was a significant difference in CDX2 expression rates between adenocarcinoma and medullary carcinoma in the meta-regression test (p < 0.001)." (PMID 35328309, 2022). "The impact of the evaluation criteria on CDX2 expression rates in medullary carcinomas was investigated." (PMID 35328309, 2022). "In medullary carcinoma, there was a significant difference in CDX2 expressions between the evaluation criteria in the meta-regression test (p = 0.003)." (PMID 35328309, 2022). "CDX2 expression rate of medullary carcinoma was significantly lower than other histologic subtypes in the meta–regression test (p < 0.001)." (PMID 35328309, 2022). "Evaluation criteria for CDX2 expression of medullary carcinoma were 0%, 10%, and 25% in previous studies." (PMID 35328309, 2022). "In medullary carcinoma subgroup, a significant difference of CDX2 expression rates between cut-offs was found." (PMID 35328309, 2022). "Furthermore, based on their histologic subtype, CDX2 expression rates of adenocarcinoma and medullary carcinoma were 0.886 (95% CI 0.837–0.923) and 0.436 (95% CI 0.269–0.618), respectively." (PMID 35328309, 2022). "However, the CDX2 expression rate of medullary carcinoma was significantly lower than that of other subtypes." (PMID 35328309, 2022). "Histologic preparations should be reevaluated by IHC to guide the search for the primary tumor: TTF-1 (pulmonary or medullary thyroid carcinoma), CDX-2 (intestinal), PAX-8, histidine-decarboxylase (pancreatic), xenin (duodenal), gastrin (occult gastrinoma), and PP/glucagon (pancreatic)." (PMID 25038902, 2014). "For example, >50% of the prognostically favourable (and frequently microsatellite-instable) medullary carcinomas as well as almost all of the biologically highly aggressive MANEC/NECs fell into the CDX2-low/absent subgroup." (PMID 34616012, 2021).
Merkel cell carcinoma (5 papers, 2007 to 2025). "However, some guidelines recommend thorough skin examination and immunohistochemical staining (IHC) for cytokeratin, TTF-1, CDX-2, and calcitonin for differential diagnoses, including paraganglioma, Merkel cell carcinoma, and MTC." (PMID 40747199, 2025). "The diagnostic value of CDX2 in Merkel cell tumor has not yet been established." (PMID 17803816, 2007). "Villin has no added value compared to CDX2 and can also be expressed in numerous non-intestinal carcinomas (bladder, Merkel cell carcinoma, sinonasal intestinal-type adenocarcinoma)." (PMID 29621151, 2018). "Therefore, the phenotype of Merkel cell carcinomas is CK7−/CK20+ (“dot-like”), CDX2−, SATB2+, Chromogranin+, Synaptophysin+ and positive for Merkel cell polyomavirus (MCPyV), while the phenotype of small cell carcinomas of the salivary glands is Synaptophin+, Chromogranin+/−, CD56+ and CDX2−." (PMID 29621151, 2018). "However, they were negative for caudal type homeobox 2, S100, paired box gene 8, thyroid transcription factor 1, and CD20, which ruled out the origin of gastrointestinal, pancreatic, lung, and Merkel cell carcinomas." (PMID 32245475, 2020).
Obesity (5 papers, 2014 to 2025). Accumulation of substantial excess body fat. "Two of these studies reported significant associations between Cdx2 SNP and obesity and its related traits." (PMID 33553043, 2020). "The most common VDR polymorphisms reported to be associated with cancer and obesity are BsmI (rs1544410), ApaI(rs7975232), TaqI (rs731236), FokI (rs2228570) and Cdx2 (rs 11,568,820)." (PMID 31395070, 2019). "Three Studies have investigated the association between the VDR Cdx2 SNP and obesity traits." (PMID 33553043, 2020). "In contrast with our findings, in a randomized control trial of 60 type 2 diabetic patients, results showed that vitamin D supplementation (25 μg/d) decreased obesity indices, including WC, body fat mass and truncal fat, only in individuals with the AA genotype of Cdx2 VDR." (PMID 31395070, 2019). "Intriguingly, immunohistochemical analysis of tumor sections from CRC patients with obesity highlighted that adipose cells, marked by high expression of adiponectin, were located at tumor invasive front and interspersed among tumor cells expressing CDX2 and covering the 28% of the entire tumor mass." (PMID 34408135, 2021).
pancreatic NETs (5 papers, 2018 to 2023). "CDX2 protein expression was reported positive in a percentage of pancreatic neuroendocrine tumors." (PMID 31249555, 2019). "CDX-2 was patchy positive in 11% of pancreatic NETs similarly seen in a previous study." (PMID 29713473, 2018). "CDX2 shows high sensitivity and specificity for small intestinal NENs, whereas PAX8 is used to identify primary and metastatic pancreatic NETs." (PMID 32245475, 2020). "In the GI and pancreatic NETs (N = 98), NKX2.2, PDX-1, and CDX-2 were immunoreactive in 82 (84%), 14 (14%), and 52 (52%) cases, respectively." (PMID 29713473, 2018). "More recently, the expression pattern of CDX-2, PAX-6, ISL-1, ER, and PR in the GI and pancreatic NET was investigated and showed small differences between the primary and metastatic NETs." (PMID 29713473, 2018). "In 98 GI and pancreatic NETs, the sensitivity and 95% confidence interval (95% CI) for NKX2.2, PDX-1, and CDX-2 were 84% (95% CI, 75% - 90%), 14% (95% CI, 8% - 23%), and 53% (95% CI, 43% - 63%), respectively." (PMID 29713473, 2018). "Consistent with the literature, no immunoreactivity for CDX-2 was seen in all 16 rectal NETs, and only 2 of 17 pancreatic NETs showed patchy immunoreactivity for CDX-2." (PMID 29713473, 2018). "Caudal type homeobox 2 (CDX-2) has been investigated previously by multiple groups and showed high sensitivity and specificity for small intestinal NET, but variable sensitivity for colorectal and pancreatic NETs." (PMID 29713473, 2018). "NKX2.2 showed higher sensitivity than CDX-2 and PDX-1 in both GI and pancreatic NETs." (PMID 29713473, 2018).
serous carcinoma (5 papers, 2016 to 2025). "In the current study, both CK7 and CK20 were negative, but CDX2 was also negative, and the histological diagnosis was serous carcinoma consistent with endometrial carcinoma tissue, leading to the diagnosis of EC metastasis." (PMID 39604765, 2024).
thymic adenocarcinoma (5 papers, 2020 to 2025). "Enteric differentiation has also been confirmed in primary thymic adenocarcinoma with the expression of CDX2 and CK20 being observed outside of the digestive system tumors such as in cases of SRCC of the urinary bladder." (PMID 36482538, 2022).
ampullary adenocarcinoma (4 papers, 2016 to 2025). "The ampullary adenocarcinoma cell lines MDA-AMP7, AVC1, RCB1280, SNU478 and SNU869 were grown in standard culture medium and expression of KRT7, KRT20, CDX2, E-Cadherin and ZEB1 mRNA was measured by real-time PCR." (PMID 26951071, 2016). "The histomolecular (morphology plus IHC) pancreaticobiliary phenotype comprises ampullary adenocarcinomas that are of pancreaticobiliary histology with negative CDX2 and positive MUC1 expression by IHC." (PMID 27549176, 2016). "Kapp et al11 from Germany retrospectively reported an exceptional response to nab‐paclitaxel and gemcitabine in 1 patient with refractory ampullary adenocarcinoma whose tumor IHC staining pattern was CK7‐positive and CK20‐ and CDX2‐negative." (PMID 31102323, 2019). "In case #1, the metastatic ampullary adenocarcinoma showed monomorphic neoplastic cells arranged in a cribriform pattern and an immunophenotype typical of adenocarcinoma of intestinal differentiation (CK20 and CDX‐2 positive and CK7 negative)." (PMID 40028792, 2025).
cervical adenocarcinoma (4 papers, 2020 to 2025). An adenocarcinoma arising from the cervical epithelium. "Moreover, CDX2 is expressed in another rare histotype of cervical cancer: intestinal type cervical adenocarcinoma." (PMID 32408525, 2020). "According to the largest study focusing on this topic, gastric type cervical adenocarcinomas are positive for CK7 in 100% of cases, CK20 in 49%, CDX2 in 51%, Ca125 in 80%, PAX8 in 68%, ER in 6%, PR in 9% and MUC6 in 81% of cases." (PMID 33706757, 2021). "Non-HPV-associated cervical adenocarcinomas of gastrointestinal origin usually express CK7, with about 50% of these tumors also expressing CK20 and CDX-2." (PMID 39040449, 2024).
clear cell carcinoma (4 papers, 2016 to 2025). "Additionally, CK7 (-) and CDX2 (-) help to exclude primary clear cell carcinoma of the gallbladder." (PMID 40395268, 2025).
colorectal adenoma (4 papers, 2011 to 2024). An adenoma that arises from the colon or rectum. "Gain of CDX2 is the second-most-frequent aberration occurring in colorectal adenomas, making it a frequent event in colorectal tumorigenesis." (PMID 39252972, 2024). "CDX2 pCTCs were detected in patients with CRC, colorectal adenoma (CAD), benign colorectal diseases (BCD), other common cancers (OCC) and normal subjects (NS)." (PMID 21364588, 2011). "In this study, the refined assay was used to evaluate the clinical significance of CDX2 pCTCs in CRC by detecting such cells in patients with CRC, colorectal adenoma (CAD), benign colorectal diseases (BCD) and other common cancers (OCC)." (PMID 21364588, 2011). "Furthermore, the CDX–2 positive phenotype indicates that both lesions of the anal canal were mucosal-based tumors, although the limited expressions of CK–7 and–20 were not typical profiles of colorectal adenomas." (PMID 26249723, 2015).